TSPAN8 (tetraspanin 8)
Diseases named in the same sentence as TSPAN8 in open-access papers (continued):
Sharing a sentence is not in itself a finding about the gene and the disease.
cancer (continued). "TSPAN8 gene played an important role in cancer initiation and overexpression was discovered in colorectal, pancreatic and NSCLC, etc." (PMID 30956756, 2019). "Our reports revealed that TSPAN8 expression enhances Hh signaling and contributes to cancer cell stemness." (PMID 31253779, 2019). "GSEA revealed that genes associated with cancer stem cells (CSC) (e.g., NES, TSPAN8, DPPP, DNAJC12, and MYC) were highly ranked and comprised 70% of the top 25 genes differentially upregulated in the DTX-resistant cells." (PMID 30100995, 2018). "Cancer cell line AS, expressing Tspan8-derived exo-somes, promotes endothelial cell proliferation and cable formation." (PMID 28977990, 2017). "Among the 33 mammalian members of the Tetraspanins family, at least five of them, CD9, CD37, CD82, CD151 and TSPAN8, are reported to display altered expression in cancers when compared to normal tissues." (PMID 28423546, 2017). "Tspan8 was shown to promote cancer cell motility through interaction with several integrins, including α6β4, α3β1 and α6β1 integrins." (PMID 25761241, 2015). "Some of the identified factors (such as TSPAN8, CXCL17, CRIP2, STARD10, CSNK2A1) and pathways (i.e. apoptosis, TGFβ, VEGF and ERK signaling) are known to participate in cancer as well as their identification here linked with airway remodeling in mustard lung." (PMID 24978043, 2014). "The data further indicate that Mycn’s interactions with Bcl11b and Tspan8 may differ between cancer and normal tissues, exhibiting a more direct interaction, observed in cancer tissues." (PMID 40862719, 2025). "This innovation was applied to the exploration of IgG repertoires from mice immunized with various antigens, including the vaccine target Tetanus Toxoid (TT), the multifunctional enzyme Neuroleukin/Glucose-6-Phosphate Isomerase (GPI), and the membrane-bound cancer target Tetraspanin-8 (TSPAN8)." (PMID 40710059, 2025). "Tetraspanins, including TSPAN8, can form complexes with specific integrin heterodimers on the surface of cancer cells and enhance the binding of cancer cells to ECM components, providing stronger adhesion points for their movement and invasion into surrounding tissues." (PMID 38275818, 2024). "Consequently, a study depicting the expression of tetraspanin 8 in clear cell renal cell carcinoma suggested its increased expression in cancer cells compared with healthy cells." (PMID 39031113, 2024). "Targeting CD151 and TSPAN8 in this context may help develop region-specific therapies for inhibiting cancer cell growth in stage 4 primary CC tumors." (PMID 38255741, 2024). "In contrast to other tetraspanins, tetraspanin 8 evidently promotes cancer progression." (PMID 39031113, 2024). "Interestingly, TSPAN8 mRNA is highly expressed in various epithelial cancers and can serve as a genetic marker for cancer stem cells or cancer-initiating cells in some cases." (PMID 38275818, 2024). "Collectively, TSPAN8 may represent a promising candidate for use as blood-based biomarkers for cancer screening." (PMID 38275818, 2024). "The functional roles of TSPAN8 have been explored in many cancers." (PMID 35246069, 2022). "The differential roles of TSPAN8 between cancers and DN may result from the difference in molecular network between cancer and inflammatory disease." (PMID 35246069, 2022). "However, TSPAN8 was recently shown to promote cancer cell stemness via activation of sonic Hedgehog signaling." (PMID 35773268, 2022). "Intriguingly, stabilization of Ptch1 by TSPAN8 promoted Ptch1 exit from and Smo accumulation in primary cilia, resulting Hh pathway activation, which was thought to mediate the role of TSPAN8 in promoting cancer stemness and chemotherapy resistance." (PMID 34948134, 2021). "In addition, the expression of TSPAN8 showed a positive relationship with the increasing metastatic ability of the cancer cells." (PMID 34163029, 2021).
cancer (continued). "Tspan8 promotes cancer metastasis and can impact leukocyte migration, but its role in immunity is largely unknown." (PMID 34871323, 2021). "Although in different types of cancers tetraspanins may interact with different partners and function discordantly, with the consistent role of TSPAN8 and its upregulation in HCC, it may also be a promising therapeutic target via a highly specific antibody." (PMID 34540692, 2021). "This is the first study reporting the role of a tetraspanin family member, Tspan8, in coordinating heterotypic crosstalk between cancer cells and surrounding epithelial cells to promote basement membrane proteolysis and stromal invasion through an MMP activation process." (PMID 32455575, 2020). "Therefore, TSPAN8 can be considered a potential therapeutic target in TSPAN8-overexpressing cancers for antibody therapy." (PMID 32138170, 2020). "Additionally, we will cover the current status of monoclonal antibodies specifically targeting TSPAN8 and the importance of TSPAN8 as an emerging therapeutic target in cancers for monoclonal antibody therapy." (PMID 32138170, 2020). "Moreover, cancer cells released exosomes containing TSPAN8 are critical for angiogenesis, as that they can be taken up and initiate angiogenic genes transcription and modulate the RNA profile in ECs or adjacent fibroblasts." (PMID 32612990, 2020). "Thus, our results suggested that NAC-increased TSPAN8 expression enable cancer cells resistant to treatment through enhanced Hh signaling and cancer cell stemness." (PMID 31253779, 2019). "However, also in other cancer types, Tspan8 can act as a regulator of proliferation, motility, and invasiveness." (PMID 30982971, 2019). "Finally, the cancer marker tetraspanin 8 (TSPAN8), which transcript was highly detected in both cell lines, was strongly reduced in co-cultures." (PMID 28726765, 2017). "In a cancer context, many studies indicate that Tspan8 promote cancer metastasis and angiogenesis." (PMID 28977990, 2017). "Besides a hypoxic profile, DTC tumors also have marked expression of cancer relevant genes such as the metastasis-promoting tetraspanin 8 (TSPAN8), proliferation and migration promoting epidermal growth factor substrate 8 (EPS8)." (PMID 27105499, 2016). "Moreover, the levels of tetraspanin-8, have been shown to be increased in cells with improved metastatic ability, and has been implied in invasiveness in several cancer types." (PMID 26196085, 2015). "In addition to cancers, TSPAN8 may play a role in other diseases by regulating the functions of a few other metalloproteases." (PMID 38275818, 2024). "In addition, tetraspanin 8 regulates proliferation, motility, and invasiveness of cancer cells." (PMID 39031113, 2024). "The expressions of two tetraspanins CD151 and TSPAN8 were found to be significantly elevated in exosomes from cancer patients, which could distinguish cancer from healthy control with AUC of 0.68 and 0.60, respectively, independently of disease stage and histological subtype." (PMID 35757760, 2022). "In addition, tetraspanin-8 can be used as an early marker for the development of this cancer." (PMID 32537468, 2020). "However, the exact function of TSPAN8 on the regulation of critical cellular activity and cancer stemness remains unclear." (PMID 31253779, 2019). "Therefore, Tspan8 appears to be an interesting target candidate for cancer treatment with mAbs." (PMID 30769765, 2019). "Research has demonstrated that the human TSPAN8 protein regulates MYC expression by binding to its promoter, enhancing STAT3’s chromatin occupancy, and influencing cancer-related gene transcription, including MYC." (PMID 40862719, 2025). "In EGFR-activated cancers, AKT phosphorylates TSPAN8 (Ser129), enabling its palmitoylation/cholesterol-dependent nuclear translocation with 14-3-3θ/importin-β." (PMID 40977744, 2025).
cancer (continued). "In particular, clusters 9, 10, 12, 13, 14, 16, 18, 19, 21, 26, 27, 28, 30, 34 and 35 not only expressed ductal cell markers (KRT19, MMP7, TSPAN8, SOX9 and LCN2), but also expressed cancer cell markers (MUC1 and PROM1)." (PMID 40362181, 2025). "Only two transcriptomic signatures reported were composed of co-expressed genes: the cancer stem cell markers CD44, CD24, and ESA; and TSPAN8 and SOX9." (PMID 39200223, 2024). "Therapeutic monoclonal antibodies (mAbs) targeting different tetraspanin members including TSPAN8, CD9, CD37 and CD151 have been explored in preclinical models and clinical trials for the treatment of hematological malignancies and carcinomas." (PMID 38275818, 2024). "In some cancer types, the pro-metastatic role of CD151 appears to be achieved through strong synergy with other tetraspanins (e.g., TSPAN8)." (PMID 33919420, 2021). "It is reported that in HCC the expression of TSPAN8 is regulated by astrocyte elevated gene-1 (AEG-1), an oncogene upregulated in various cancers; and TSPAN8 acts as one essential effector on its pro-metastasis effect." (PMID 34540692, 2021). "Based on the available evidence, CD81 and CD82, and TSPAN6 can serve as cancer suppressors, while CD151, TSPAN1, and TSPAN8 act as cancer promoters in the diagnosis and prognosis of HCC patients." (PMID 34540692, 2021). "In these cells, TSPAN8 enhances Sonic Hedgehog (SHH) signaling, stabilizes the expression of protein patched homolog 1 (PTCH1) by recruiting ataxin-3 (ATXN3), and promotes cancer stemness." (PMID 32138170, 2020). "In gastric cancer, the effect of such exosomal proteins as tetraspanin-8 and DC97 on the growth and metastasis of cancer cells has been proven." (PMID 32537468, 2020). "We quantified by an ELISA-based technique specific proteins of cancer-derived exosomes (CD44,CD44v6,EpCAM,CD9,CD81,Tspan8,Integrin α6,Integrin β4,CD24,CXCR4)." (PMID 31048929, 2019). "Considering the complexity and heterogeneity of CSCs, TSPAN8 can be used as a molecular marker in combination with other CSCs markers, such as ALDH1 and CD44+/CD24−, to define cancer cell stemness." (PMID 31253779, 2019). "Among the human tetraspanins, Tspan8 and 12, CD9, CD37, CD63, CD81, CD82, and CD151 play a role in cancer progression." (PMID 29946318, 2018). "The pro- or anti- cancer properties of CD9 is still controversial, while CD151 and TSPAN8 are assumed to display oncogenic activities." (PMID 28423546, 2017). "Of these genes, we selected TSPAN8, BST2, BMP7, and Col6A1 for further analysis, because these genes have been reported to be involved in tumorigenicity or cancer cell invasion and migration." (PMID 25221999, 2014). "Given the critical roles of TSPAN8, UCHL1, and MYC in key biological processes in aggressive cancers like SCLC, targeting these molecules may offer valuable therapeutic potential." (PMID 40428124, 2025). "The findings indicated that the markers CD151, CD171, and tetraspanin 8 were the most effective in distinguishing patients with cancer, regardless of histological subtype, from those without cancer." (PMID 41573685, 2025). "It is possible that Tspan8 regulates additional ADAM17 substrates that are involved in intra- and extravasation, which were not part of this study, leading to enhanced metastasis of Tspan8-expressing cancer cells." (PMID 36078095, 2022). "As demonstrated in the top DEGs, specifically cancer stem lineage clusters expressed high levels of stemness feature genes including ALDH1A1, PROM1, and NES, while ductal lineage cluster expressed high levels of ductal markers such as MMP7, TSPAN8, and SOX9." (PMID 34732701, 2021). "Interestingly, by combining TSPAN8 and LGALS4, which display specular expression in cancer and/or normal blood (TSPAN8 is higher in CRC blood, whereas LGALS4 is lower), we detected promising values of sensitivity and specificity compared to the markers alone." (PMID 26993598, 2016).
cancer (continued). "However, whether enhanced TSPAN8 expression in CAFs and other stromal cells has an effect on the regulation of EMT, the invasion of cancer cells and cancer metastasis remains largely unknown." (PMID 38275818, 2024). "However, because elevated Tspan8/Thrsp expression was accompanied by an interferon response in our model, we next investigated whether BRCA2-mutant cancers displayed increased interferon response pathway expression." (PMID 37626143, 2023). "Furthermore, it was shown that cancer cells that express TSPAN8 metastasize uncontrollably and do not stop at the lymph nodes." (PMID 34830819, 2021). "However, both TSPAN8 and THRSP expression were lower in BRCA2-mutant and non-BRCA2-related cancers when compared to normal tissue." (PMID 37626143, 2023). "The markers CD151, CD171, and TSPAN8 were the most effective in differentiating cancer patients of all histological subtypes from those without cancer, with CD151 showing AUC of 0.68 (p = 0.0002), CD171 showing AUC of 0.60 (p = 0.0002) and TSPAN8 showing AUC of 0.60 (p = 0.0002)." (PMID 40575159, 2025).
adenocarcinoma (3 papers, 2019 to 2022). A common cancer characterized by the presence of malignant glandular cells. "Rana and colleagues found that EVs obtained from the rat adenocarcinoma cell line were enriched in Tspan8 associated with CD49d, but not with CD49c, CD9, CD81, or CD151." (PMID 33003285, 2020).
digestive system cancer (2 papers, 2012 to 2024). A primary or metastatic malignant neoplasm involving any part of the digestive system. "Generally, the expression of CD9, CD151, Tspan1, Tspan5, Tspan8, Tspan12, Tspan15, and Tspan31 are upregulated, facilitating the migration and invasion of digestive system cancer cells." (PMID 38389703, 2024).
digestive system tumor (2 papers, 2014 to 2024). "Conversely, CD9, CD151, Tspan8, Tspan1, Tspan5, Tspan31, Tspan12, and Tspan15 are upregulated and enhance digestive system tumor cell metastasis." (PMID 38389703, 2024).
infection (2 papers, 2023 to 2024). The state of being infected such as from the introduction of a foreign agent such as serum, vaccine, antigenic substance or organism. "Blocking TSPAN8 in airway epithelial organoids prior to infection is associated with a decrease in the viral load of AOs." (PMID 36827975, 2023). "We measured the expression of LAMP-1 (human), a transmembrane glycoprotein that can be found in lysosomes, ATPase, and TSPAN8 transmembrane protein in CRFK-derived EVs’ post-infection." (PMID 39091390, 2024). "Expression of several transmembrane molecules such as LAMP-1 (human), ATPase, and TSPAN8 transmembrane proteins was significantly upregulated in CRFK cell-derived EVs’ post-infection." (PMID 39091390, 2024). "The number of TSPAN8-positive cells increased upon SARS-CoV-2 infection but decreased upon H1N1/PR8 infection." (PMID 36827975, 2023). "While AO cell infection rates decreased sequentially in SARS-CoV-2 from WA-1 to Delta to Omicron variants, the presence of TSPAN8 in infected cells remained conserved." (PMID 36827975, 2023). "We demonstrated that the addition of a TSPAN8-blocking antibody to the AO prior to infection decreased SARS-CoV-2 infection." (PMID 36827975, 2023). "Different from ACE2, the proportion of TSPAN8+ cells prior to infection correlated with levels of eventual infection, suggesting TSPAN8 somehow facilitates SARS-CoV-2 infection." (PMID 36827975, 2023). "We think that TSPAN8 contributes to the spreading of infection through EVs in the case of SARS-CoV-2 infection." (PMID 36827975, 2023). "Single-cell RNA sequencing (scRNA-seq) and Spectral flow enabled the discovery of Tetraspanin-8 (TSPAN8) as a conserved mediator of SARS-CoV-2 Ancestral (WA-1)-, Delta-, and Omicron-variant infection." (PMID 36827975, 2023). "These correlations also held true for TSPAN8+ACE2+ and TSPAN8+MUC5AC− cells prior to infection." (PMID 36827975, 2023). "Last, we investigated the infection characteristics of SARS-CoV-2 WA-1, Delta, and Omicron variants in the context of 3D AO with their diverse cell-type composition and subsequently related results to TSPAN8." (PMID 36827975, 2023). "Infection levels of 2522UL and 2450UL organoids with SARS-CoV-2 WA-1 were reduced by 60% upon TSPAN8-blocking antibody treatment, demonstrating that TSPAN8 plays a functional role in SARS-CoV-2 infection." (PMID 36827975, 2023).
hematological malignancies (1 paper, 2021). "CAPN10 plays important roles in the translocation of glucose transporter 4 (GLUT4), secretion of insulin and apoptotic processes in pancreatic cells, while TSPAN8 has been described as a prognostic indicator for patients with certain solid tumors, but not for hematological malignancies." (PMID 34502231, 2021).
TSPAN8 also shares sentences with these, for which no sentence is quoted: colon adenocarcinoma (3 papers); colorectal tumors (3); chronic pancreatitis (2); diabetes (2); glioblastoma (2); renal cell carcinoma (2); bladder cancer (1); dementia (1); diabetic nephropathy (1); escherichia coli infection (1); hyperlipidemia (1); hypopharyngeal cancer (1); Impaired glucose tolerance (1); Infertility (1); inflammatory bowel disease (1); Insulin resistance (1); intrahepatic cholangiocarcinoma (1); lung (1); neuroblastoma (1); nicotine addiction (1); pancreatic (1); rectal cancer (1); rheumatoid arthritis (1); sarcoma (1); squamous cell carcinoma (1); triple-negative breast carcinoma (1).